SMAD3 (SMAD family member 3)
Diseases named in the same sentence as SMAD3 in open-access papers (continued):
Sharing a sentence is not in itself a finding about the gene and the disease.
breast carcinoma (continued). "With respect to this, we have preliminary evidence that over-expression of RARα2 in a retinoid-responsive breast-cancer cell line inhibits ATRA-simulated activity of a RARE-containing reporter and suppresses ATRA-dependent induction of the retinoid targets, SMAD3 and β-catenin." (PMID 27419624, 2017). "This SMAD3 A382V mutation has, according to the COSMIC database, been observed in breast cancers but not in CRC before and is classified as potentially pathogenic with a high likelihood of a gain of function in terms of an additional phosphorylation site." (PMID 27087592, 2016). "Interestingly, Smad3 can also complex with YAP/TAZ-TEAD and cooperatively induce the expression of CTGF downstream of TGFβ signaling in breast cancer cells." (PMID 26876920, 2016). "The depletion of Bcl-3 in breast cancer cells reduced the steady-state levelsof Smad3 protein upon TGFβ stimulation but no change in theSmad3 mRNA level." (PMID 27906182, 2016). "Smad3−/− mice cannot be used for analysis of spontaneous mammary tumor formation, as they do not survive beyond at most 8 months due to certain defects." (PMID 27588495, 2016). "Although Smad2 and Smad3 are key elements in the Smad signaling pathway, they may play distinct roles in the induction of the EMT in breast cancer." (PMID 25962958, 2015). "In the absence of WWOX, a condition that emulates advanced breast cancer, SMAD3 can enter the nucleus uninhibited." (PMID 24330518, 2013). "In addition to the regulation of Smad3-specific transcription, 14-3-3σ phosphorylation at Ser69 and Ser74 regulates the CSC-like features of breast cancer cells." (PMID 23741479, 2013). "In conclusion, by supporting TGFβ/Smad3 signaling cAMP may enhance TGFβ/Smad3-induced EMT, generation of CSCs and breast cancer metastasis, thereby, deteriorate the outcome of breast cancer patients." (PMID 23349840, 2013). "To study the cross-talk between the cAMP and the TGFβ signaling pathways in breast cancer cells we chose MDA-MB-231 cells, because they express functional TGFβ receptors I and II and respond to TGFβ by nuclear translocation of Smad3 and upregulation of TGFβ-responsive genes, such as PTHrP and PAI-1." (PMID 23349840, 2013). "This is interesting in light of previous reports indicating that overexpression of a dominant negative form of Smad3 reduced the ability of cancer cells to metastasize and that Smad3, but not Smad2, promotes breast cancer metastasis in mice." (PMID 22995475, 2012). "SMAD3 also contributes to the 3-indole-induced G1 arrest in cancer cells and its inhibition depends on CCND1-CDK4 (cyclin-dependent kinase 4) action in breast cancer cells overexpressing CCND1, which appeared upregulated by A1789T." (PMID 22646717, 2012). "Collectively, these data indicate that TGFβ potently induces p21 expression in a Smad3-dependent manner without affecting cell growth or cell cycle progression in invasive human basal-type breast cancer cells." (PMID 22995475, 2012). "Nevertheless, aberrant germline expressions of SMAD3 and SMAD4 may be more common in breast cancer than previously suspected and offer novel insight into their roles in predisposition and/or progression of breast cancer." (PMID 21835029, 2011). "Nevertheless, significantly higher mean expression levels in the grouped breast cancer (BC) versus control (CO) (P = 0.02) (data not shown), strongly suggests SMAD3 germline expression to be an important factor in breast cancer." (PMID 21835029, 2011). "Based on current understanding, mutations in SMAD3 are absent in almost all cancer types while mutations of SMAD4 are frequent in pancreatic and colorectal cancers but rare in breast cancer." (PMID 21835029, 2011). "Here, we aimed to explore the mutation spectrum of SMAD3 and SMAD4 by screening the highly conserved MH2 domain in the germline DNA in familial and non-familial breast cancer cases as well as age, gender and ethnicity matched healthy population controls." (PMID 21835029, 2011).
breast carcinoma (continued). "Further, WT-BRCA1, but not mutated BRCA1 increased the expression of Smad3 protein in a dose-dependent manner, while silencing of WT-BRCA1 by siRNA decreased Smad3 and Smad4 interaction induced by TGF-β in MCF-7 breast cancer cells." (PMID 19768112, 2009). "In contrast, ATP7A, DLK1, CRBP1, and SMAD3 were not modulated by aRA in RA-sensitive lung and breast cancer cells." (PMID 16012519, 2005). "Additionally, TB activated immune-related pathways via ERK/MAPK signaling and upregulated genes such as SMAD2, SMAD3, and JUN.Conclusions: TB functions as an HSP90 inhibitor with dual anticancer and immunomodulatory properties in Estrogen Receptor-Positive (ER+) breast cancer cells." (PMID 41304910, 2025). "Thus, our findings suggest that ZNF8 acts as a selective coactivator of the TGF‐β/Smad3 pathway, specifically facilitating lung metastasis in breast cancer while not impacting tumor cell proliferation." (PMID 39225541, 2024). "With respect to the mechanisms of ROCK in the presence of TGF-β, a study in human breast cancer cells showed that Rho/ROCK is able to phosphorylate the linker region of Smad3 and thereby alter the effect of TGF-β without affecting carboxy-terminal phosphorylation." (PMID 38710741, 2024). "Furthermore, leptin was reported to stimulate the secretion of TGFβ, which leads to the activation of SMAD family member 2 (Smad2), Smad3, and Smad4 transcription factors, the repression of cadherin 1 (CDH1) coding for E-cadherin, and an increased CSC phenotype in breast cancer cells." (PMID 36010901, 2022). "In addition, MES TFs, SMAD3, SOX9, WWTR1, and IFI16 had 32, 23, 6, and 5 connections, respectively, and KEGG gene enrichment analysis revealed enrichment for ‘breast cancer’, ‘prostate cancer’, and ‘hepatocellular carcinoma’ processes in addition to ‘miRNA in cancer’ terms." (PMID 35201514, 2021). "Moreover, PSG9 enhanced the stability of Smad2, Smad3, and Smad4 proteins by blocking their proteasomal degradation, and regulated the expression of TGF‐β1 target genes involved in EMT and breast cancer progression, thus further amplifying the canonical TGF‐β/Smad signaling in breast cancer cells." (PMID 33377651, 2020). "During breast cancer bone metastasis progression, the TGF-β induced bone metastatic genes expression were found depend on SMAD3 but not SMAD2, and knockdown of SMAD3 in MDA-MB-231 cells inhibited bone metastasis, while SMAD3 knockdown led to a more aggressive phenotype." (PMID 32746934, 2020). "The Smad3+/− (heterozygous) mice do not form spontaneous mammary tumors (data not shown)." (PMID 27588495, 2016). "HDAC inhibitors may affect the expression/activity of other transcription factors known to regulate ZFP36 transcription such as Smad3, Smad4, AP1, c-myc or NFκB but also some microRNAs, such as miR-29a, which downregulates TTP in a breast cancer model and is known to be upregulated in colon cancer." (PMID 26343742, 2015). "Presently, it is not known whether SMAD3 and SMAD4 germline alterations are involved in breast cancer predisposition." (PMID 21835029, 2011). "However, Smad3 protein loss is not common in skin SCC and increased Smad3 expression has been reported in breast cancer." (PMID 22204491, 2011). "However, germline mutation analysis of SMAD3 and SMAD4, the principle substrates of the TGF-β signaling pathway, has not yet been conducted in breast cancer." (PMID 21835029, 2011). "Moreover, the overexpression of FOXM1 in breast cancer can interact with Smad3/Smad4 and inhibit the binding of TIF1γ to Smad4 to prevent its ubiquitination, which can attenuate the inhibitory effects of TIF1γ on TGF-β signaling to promote the metastasis of breast cancer." (PMID 31632911, 2019). "Furthermore, we hypothesize that the upregulated cyclin E activity in trastuzumab resistant HER2 positive breast cancer facilitates CDK2 mediated non-canonical Smad3 phosphorylation, resulting in cell cycle progression and oncogenesis." (PMID 29137393, 2017).
breast carcinoma (continued). "And the correlation between BCL6, NFIB and SMAD3 is only present in CRPC tumor tissues and not in CSPC tumor tissues or other adenocarcinoma tissues (e.g., esophageal cancer and breast cancer)." (PMID 40470696, 2025). "Conversely, expression of Smad2, Smad3, alone or together promoted an EMT-like phenotype even in the absence of exogenous TGFβ in breast carcinoma organoids." (PMID 37414747, 2023). "Our study indicated that GluOC can effectively improve the expression of TGF-β/SMAD3 in MDA-MB-231 cells, while GluOC did not have effects on MCF7 breast cancer cells." (PMID 35413833, 2022). "The results demonstrated that GluOC can significantly promote the proliferation and migration of MDA-MB-231 cells via the TGF-β/SMAD3 signaling pathway, but there was no obvious influence on MCF7 breast cancer cells." (PMID 35413833, 2022). "This review focuses on breast cancer, and highlights advances in the understanding of CDK-mediated noncanonical SMAD3 phosphorylation." (PMID 34771508, 2021). "Expression of p-SMAD3 was not significantly changed upon KRT19 knockdown in colon and breast cancer cells." (PMID 30650643, 2019). "MCF-7 breast cancer cells as well as non-malignant HaCaT cells and primary keratinocytes were exposed for 24 h to 2 ng/ml TGF-β followed by measurement of phospho-S423/S425 Smad3." (PMID 33295886, 2020). "SMAD3 was identified as a non-histone substrate of lysine acetyltransferase 6 A (KAT6A) and the acetylation of SMAD3 at K20 and K117 by KAT6A leads to enhanced breast cancer stem-like cell stemness, myeloid-derived suppressor cell recruitment, and triple-negative breast cancer (TNBC) metastasis." (PMID 40164592, 2025). "Thus, we checked the expression of p-SMAD3 in KRT19 knockdown colon and breast cancer cells, but there was no significant change observed upon KRT19 knockdown, suggesting that β-catenin/SMAD3 mediated Wnt signaling activation was not involved in this phenomenon." (PMID 30650643, 2019). "Smad2 and Smad3 are highly homologous, but may play non-redundant or even opposing roles in TGF-β signaling, so we first wished to determine which Smad was more important for tumor suppression in the MCF10-based breast cancer model." (PMID 24890385, 2014).
liver fibrosis (228 papers, 2010 to 2026). "Taken together, our findings suggest that downregulation or ablation of Ufbp1 leads to Smad3 activation, elevated ER stress, and hepatocyte apoptosis, which in turn causes liver fibrosis." (PMID 34307359, 2021). "The phosphorylation of Smad3 and its subsequent nuclear translocation are critical steps in the signaling cascade underlying liver fibrosis." (PMID 32120837, 2020). "The inhibitory effect of kahweol on hepatic fibrosis was associated with downregulation of TGF-β-stimulated phospho-Smad3, STAT3, ERK, and JNK expression." (PMID 29152065, 2017). "CCl4-induced hepatic fibrosis caused increased phosphorylation of Smad2 and Smad3 when compared to that of the controls." (PMID 25373883, 2015). "The phenomenon was confirmed by another set of animal experiments with SMP30 KO mice, indicating that SMP30 deficiency increases the levels of phospho-Smad3 which is a key protein to promote liver fibrosis." (PMID 24304543, 2013). "In present study, we evaluated the effect of Smad3 deficiency in Smad3−/− mice with carbon tetrachloride (CCl4)-induced liver fibrosis." (PMID 24304543, 2013). "In this study, the expressions of four proteins closely associated with the TGF-β/Smad3 signal transduction pathway determining the pathological process of hepatic fibrosis were detected." (PMID 24693382, 2013). "A major finding of the present study is that Smad3 deficiency significantly prevented CCl4-induced liver fibrosis by reducing antioxidant protein expression as well as blocking TGF-β signaling in the liver." (PMID 24304543, 2013). "In the context of liver fibrosis, Smad3 is pathogenic because mice null for Smad3 are protected against dimethylnitrosamine-induced hepatic fibrosis." (PMID 22363627, 2012). "SMAD3 signalling was mechanistically linked to the liver fibrosis development in mice." (PMID 36768453, 2023). "Previous studies also showed that PM2.5 exposure alone could cause mild hepatic fibrosis and activation of the TGFβ-Smad3 signaling pathway." (PMID 32182211, 2020). "In addition to tumor growth, Smad3+/− VD-deficient mice also exhibit increased liver fibrosis compared to controls, reflective of epithelial-mesenchymal transition (EMT) in liver tissues in the mutant mice." (PMID 27456065, 2016). "It had been reported that suppressing the activation HSCs and expression of TGF-β1 could reduce the levels of myofibroblast markers, increase the ratio of MMPs/TIMPs, and decrease Smad2/Smad3 associated collagen production which further attenuated liver fibrosis." (PMID 33574836, 2021). "Pharmacological inhibition of MAGL using MJN110 resulted in reduced CB1R expression and decreased levels of the apoptosis marker SMAD3, indicating a reduction in liver fibrosis and hepatocyte apoptosis, respectively." (PMID 42306226, 2026). "FN significantly ameliorated portal pressure in cirrhosis-induced PHT, improved liver function, and reduced liver fibrosis and hepatic stellate cell activation with decreased SMAD3 protein expression." (PMID 40852727, 2025). "Genetic VDR deletion in mice exacerbated liver fibrosis progression, which was associated with elevated TGF-β1 levels and increased Smad3 phosphorylation." (PMID 40514735, 2025). "Past studies have shown that SMAD3 is the key progenitor in the induction of liver fibrosis, although both SMAD2 and SMAD3 are substrates that are significantly activated in liver fibrosis." (PMID 39937012, 2025). "Given the central role of the TGF-β1/Smad3 pathway in promoting hepatic fibrosis through ECM accumulation, these findings support PACs-CFE’s role in attenuating fibrogenic signaling." (PMID 41228535, 2025). "It is widely acknowledged that the TGFβ1/SMAD3 pathway plays a key role in excessive ROS generation in liver fibrosis, and TGFβ1 can regulate NOX4/ROS pathway through SMAD3 signaling." (PMID 40060764, 2025).
liver fibrosis (continued). "Overall, our study demonstrates that GSH can improve the engraftment efficiency of ADSCs in liver fibrosis by inhibiting the TGFβ1/SMAD3/NOX4 signaling pathway." (PMID 40060764, 2025). "The association between liver fibrosis and decreased hepatic expression of XPO4 has been demonstrated to occur via transforming growth factor-β (TGF-β)/SMAD3 signaling." (PMID 38722973, 2024). "This polyphenol can also act on transforming growth factor beta 1 (TGF-β1)/SMAD3, reducing liver fibrosis." (PMID 39458995, 2024). "Research suggests that blocking the TGF-β signaling pathway by inhibiting Smad3 phosphorylation can effectively and safely reduce liver fibrosis in animal models." (PMID 38468370, 2024). "Upregulating the expression levels of α-SMA and COL1α1via the transforming growth factor-β (TGF-β)/small mother against decapentaplegic family member 3 (SMAD3) signaling pathway in liver tissues and leading to hepatic fibrosis." (PMID 39314046, 2024). "Based on correlation between Sirt6 and fibrosis/Smad signaling pathway, it had been reported that Sirt6 directly interacted with Smad2 in hepatic fibrosis and there was a physical interaction between Sirt6 and Smad3 in hepatic stellate cells." (PMID 38789630, 2024). "For instance, ghrelin administration therapy dramatically decreased TGF-β1 and p-Smad3 protein expression in a mouse model of hepatic fibrosis, as well as reduced extracellular matrix formation and myofibroblast accumulation (Ref." (PMID 39569809, 2024). "The functional role of TGF-β/Smad signaling in liver fibrosis has been demonstrated by the finding that Smad3 downregulation ameliorated dimethylnitrosamine-induced hepatic fibrosis." (PMID 39512816, 2024). "Long-term exposure to TAA can activate downstream signaling of TGF–β/Smad3 in damaged liver cells, enabling hepatic stellate cells to acquire a myofibroblast like phenotype, leading to liver fibrosis." (PMID 39519763, 2024). "The in vivo experiments also showed significantly increased expression of TGF-β1 and Smad3 in the male model group compared with the female model group, suggesting that alcohol-induced liver fibrosis is more prominent in male mice." (PMID 38408944, 2024). "The activation of the TGF-β/SMAD signaling pathway in HSCs resulted in the upregulation of several key genes associated with hepatic fibrosis, including TIMP1, SMAD2, SMAD3, COL1A1, and MMP2, as well as increased secretion of MMP-9 protein." (PMID 39201682, 2024). "Smad3 negatively regulates miR-29b expression, which directly drives the TGF-β/Smad3 pathway and induces liver fibrosis." (PMID 39063116, 2024). "A recent study revealed decreased XPO4 hepatic expression with advancement of liver fibrosis through regulation of transforming growth factor beta (TGF-β)/SMAD3/SMAD4 -mediated HSC activation." (PMID 38722973, 2024). "In vivo administration of LIN significantly ameliorated carbon tetrachloride (CCl4)-induced HSC activation and liver fibrosis by inhibiting the TGFβ/Smad3 pathway." (PMID 36843936, 2023). "Smad3, a key mediator of TGF-β-activated fibrotic processes, has been implicated in liver fibrosis mitigation." (PMID 38059910, 2023). "The increased Smad3 positively regulates circTUBD1, leading to the continuous accumulation of intracellular Smad3 and exacerbation of liver fibrosis." (PMID 37814303, 2023). "Further investigation into the mechanisms by which SREBP1c regulates HSCs and liver fibrosis demonstrated that overexpression of SREBP1c inhibited liver fibrosis in mice by reducing the levels of TGFβ1 and signaling via SMAD3 and Akt1/2/3." (PMID 38137501, 2023). "The mRNA expression of TGF-β, αSMA, and collagen1α genes, and the level of Smad3 protein were measured to assess liver fibrosis." (PMID 37275763, 2023). "Isorhamnetin protects against liver fibrosis via inhibition of TGF-β1-mediate Smad3 and p38 MAPK signaling pathways." (PMID 37167198, 2023).